PLK2 (polo like kinase 2)
Diseases named in the same sentence as PLK2 in open-access papers (continued):
Sharing a sentence is not in itself a finding about the gene and the disease.
tumor (continued). "Moreover, expression of PLK2 were found to be remarkably suppressed in all 4 molecular subtypes of GBM including classical (CL), mesenchymal (MES), neural and proneural (PN) when compared to non-tumor tissues." (PMID 33176854, 2020). "Unlike PLK1, PLK2 functions as a tumor suppressor in some cancer types." (PMID 33176854, 2020). "However, because Plk2 and Plk3 have functions akin to tumor suppression, it is desirable to inhibit Plk1 and not other Plks." (PMID 27874094, 2016). "The tumor suppressors genes such as EFNA1 (Ephrin-A1), ERRFI1 (ERBB Receptor Feedback Inhibitor 1), LATS2 (Large Tumor Suppressor Kinase 2) and PLK2 (Polo-Like Kinase 2) also show higher average expression in PD0325901 resistant cell lines and thus may be contributing to PD0325901 resistance." (PMID 27030518, 2016). "However, in nonresponders, although volasertib slowed tumor growth of the model with lower PLK2 expression (BCM-4664), there was one exception where it induced a complete response in the PDX model with higher PLK2 expression (HCI-027)." (PMID 35156101, 2021).
cancer (44 papers, 2012 to 2026). A tumor composed of atypical neoplastic, often pleomorphic cells that invade other tissues. "Beroukhim and colleagues reported previously that chromosome 5q loss containing PLK2 was one of the top 20 most significant peak deletion regions detected across 26 types of human cancers." (PMID 35156101, 2021). "Among atypical ISGs, we implicated PLK2 as one mediator of the observed cancer cell ICD." (PMID 36646704, 2023). "In summary, thisstudy identified novel PLK2 inhibitors that serve as promising startingpoints for the development of PLK2-targeted cancer therapeutics." (PMID 41405409, 2026). "PLK2 is a highly conserved serine/threonine kinase predominantly studied in neurodegenerative diseases and cancer, with limited research on its role in glycolysis and inflammation." (PMID 41019094, 2025). "To explore the role of PLK2 in EBV-related cancers, we first examined its effects on NPC and GC cell lines." (PMID 40059116, 2025). "Among the atypical ISGs in IFN treated USP18 depleted cancer cells, we identified PLK2 as one mediator of the observed ICD." (PMID 38799433, 2024). "Enhanced levels of PLK2 correlated with high levels of caspase-3 and GSDME cleavage, a hallmark of pyroptosis, in IFN treated USP18-/- cancer cells." (PMID 38799433, 2024). "Enhanced levels of PLK2 correlated with high levels of GSDME cleavage, a hallmark of pyroptosis, in IFN-treated USP18−/− THP-1 and MDA-MB-231 cancer cells." (PMID 36646704, 2023). "We also found recurrent CRISPR-induced indels from both NRASG12V and KRASG12D screens in genes whose loss has been linked to ICC but that have not previously been shown to genetically interact with mutant RAS in this cancer including Brca2, Nf2, and Plk2." (PMID 35074757, 2022). "Other significantly over-expressed genes in radioresistant PDOs – namely PLK2, UBASH3B, and NTN1 – have been associated with cancer progression." (PMID 35860583, 2022). "Several kinases associated with cancer cell survival, including KS6A2/RPS6KA2 and PLK2, are also amongst this gene set." (PMID 34359681, 2021). "In the same malignancy, the transcription factor forkhead box family member FOXD1 promotes PLK2 expression on mRNA and protein levels resulting in increased proliferation and suppressed apoptosis of cancer cells." (PMID 34065956, 2021). "The authors proposed the disruption of the PLK2 activity as an interesting idea for a new anti-cancer drug." (PMID 33287223, 2020). "In a cancer cell, this activity changes its face—the antiproliferative impact of PLK2 during mitosis leads to drug resistance and its role reverses to pro-oncogenic." (PMID 33287223, 2020). "Compared with the abundant evidence of PLK1 inhibitors against several cancer types, the evidence regarding PLK2 inhibitors is limited." (PMID 32878237, 2020). "As a result, 39 cases (70%) showed significant down-regulation of PLK2 in cancer tissues compared to the controls." (PMID 25239093, 2014). "While PLK1 has been pre-clinically validated as a cancer target and is generally overexpressed in different forms of human tumors, PLK2 has been initially described as a tumor suppressor gene." (PMID 25338102, 2014). "The polo-like kinase PLK2 has recently been identified as a potential theranostic marker in the management of chemotherapy sensitive cancers." (PMID 22289679, 2012). "We have shown that the cell cycle regulators PLK2 and p57Kip2 are important determinants and candidate novel biomarkers of chemotherapy resistance in ovarian (and potentially other) cancers." (PMID 22289679, 2012). "Polo-like kinase 2 (PLK2), a member of the polo-like kinase family, has been variably implicated in cancer, but its role in GBM has not been fully elucidated." (PMID 39927502, 2025). "Even though the function of Plk2 in cancer may depend on tissue-specific characteristics, most studies on Plk2 have focused on defense mechanisms in response to oxidative stress in cellular damage." (PMID 35842499, 2023).
cancer (continued). "Importantly, we showed that ectopic expression of PLK2 in several types of cancer cells promoted processing of Caspase-3, cleavage of GSDME, DAMPs release, and cell death, but not IL-1β secretion." (PMID 36646704, 2023). "PLK2 was regarded as contradictory role in cancer development." (PMID 34080290, 2021). "Unlike the well-established oncogenic function of PLK1, the role of PLK2 in human cancers remains unclear." (PMID 35156101, 2021). "TNBC, and other cancers with low PLK2 expression, are such candidates to leverage precision medicine to identify patients who might benefit from treatment with these inhibitors." (PMID 35156101, 2021). "Based on the results of this and a limited number of preclinical studies, PLK2 could also serve as a potential therapeutic target for several cancer types by regulating apoptosis and cell proliferation." (PMID 32878237, 2020). "The roles of PLK2–5 in cancer glucose metabolism remain to be elucidated." (PMID 31655629, 2019). "Consequently, USP18 suppression not only enhances expression of canonical IFN-stimulated genes (ISGs), but also activates the expression of a set of atypical ISGs and NF-κB target genes, including genes such as Polo like kinase 2 (PLK2), that induce cancer pyroptosis." (PMID 36646704, 2023). "However, the function of PLK2 and PLK3 remains unclear, in cancer cells PLK2 and PLK3 exist as important mediators of stress phenotypes in response to DNA damage or oxidative stress." (PMID 23056340, 2012). "The visibility of tissue sections was evident, with a notable increase in VEGFA and PLK2 expression in ITM (n = 25) and IE2 (n = 1) cancer tissues compared to the ID group (n = 24)." (PMID 39865865, 2025). "Despite being known for its potential among other PLK types (PLK2, PLK3, PLK4, and PLK5), PLK1 is determined recently as a potential oncogenic target across various cancer types due to its extensive research exploration and essential mitotic roles." (PMID 41404416, 2025). "The specific effects of SR1848, which inhibits NR5A2, ON1231320 or BI2536, which inhibits PLK2, and blebbistatin, which inhibits MYH10, were further validated in cancer cell lines." (PMID 39814695, 2025). "We found that DEGs, such as CDKN1C, NEDD4L, PLK2 and SOX4, were closely related to the occurrence and development of malignant tumors." (PMID 38520027, 2024). "Although the beta-carboline compounds can inhibit the kinase activity of PLK1, PLK2 and PLK3, it is likely that the inhibition of PLK1 contributes to toxicity of these compounds to cancer cells." (PMID 23056340, 2012). "USP18 suppression could induce cancer cell GSDME-dependent pyroptosis and suppress leukemogenesis via upregulating PLK2, an atypical ISG." (PMID 39048945, 2024). "Although the Notch signaling has been clarified to be involved in the progression of various cancers, the correlation of Notch1 and PLK2 has not been investigated." (PMID 33176854, 2020). "The FOXM1 transcription factor is a proto-oncogene involved in cell cycle progression, cell proliferation, tumorigenesis and cancer progression, and many of its target genes (> 20) were downregulated in paclitaxel-residual MDA-MB-231 cells including AURKB, CCNB1, PLK1, PLK2, and the kinesin KIF20A." (PMID 28187446, 2017). "Importantly, we demonstrated that the ectopic expression of PLK2, independent of its kinase activity, in several types of cancer cells promoted the caspase-3 processing, GSDME cleavage, DAMPs release, and cell death, albeit without IL-1β secretion." (PMID 38799433, 2024). "Therefore, the utility of PLK2 as a biomarker may have a broader application and provide a therapeutic window for the use of PLK1 inhibitors in multiple types of cancers." (PMID 35156101, 2021).
cancer (continued). "In addition, expression of Kruppel-like factor 4 (KLF4), Ras guanyl nucleotide exchange factor 1A (RASGEF1A), and polo-like kinase 2 (PLK2) have been reported to exhibit anti-apoptotic and growth-promoting activity in human cancer cells and are also up-regulated by RASSF1C over-expression." (PMID 22591718, 2012).
neurodegenerative disease (8 papers, 2017 to 2025). A disorder of the central nervous system characterized by gradual and progressive loss of neural tissue and neurologic function. "The effect of PLK2 in inhibiting hematological tumors and fibrotic diseases, as well as participating in neurodegenerative diseases, has been gradually recognized." (PMID 35898867, 2022). "The use of PLK2 inhibitors to treat neurodegenerative diseases such as PD has become a possible option and will be reviewed below." (PMID 35898867, 2022). "PLK2 has vital functions in postmitotic neurons during the process of neurodegenerative disease, such as PD." (PMID 31697645, 2019). "PLK2 plays an important role in many aspects, e.g., cell cycle, cell differentiation, ontogenesis, stress response, tumorigenesis, neurodegenerative diseases, inflammation and injury." (PMID 35898867, 2022). "Additionally, the protein–ligand docking and interaction profiling studies could predict the potential inhibitory effect of the DHE-derived IR3G/IR on AChE, MAO-B, and PLK2, which could improve neurodegenerative diseases, including PD." (PMID 35270118, 2022).
infection (6 papers, 2016 to 2024). The state of being infected such as from the introduction of a foreign agent such as serum, vaccine, antigenic substance or organism. "We found that aMPV/C infection triggers apoptosis and ROS generation in Vero cells, which is inhibited by PLK2 siRNA." (PMID 32231136, 2020). "To investigate the function of PLK2 in aMPV/C infection, we suppressed PLK2 expression using PLK2-specific siRNAs." (PMID 32231136, 2020). "We found that PLK2 expression was upregulated and further examined its biological function in aMPV/C infection." (PMID 32231136, 2020). "Besides, avian metapneumovirus subtype C (aMPV/C) infection leads to upregulation of PLK2 in mammalian cells." (PMID 35898867, 2022). "In the proteomics database, PLK2 expression was increased by aMPV/C infection at 48 hpi." (PMID 32231136, 2020). "In this analysis, we found that PLK2 expression was upregulated by aMPV/C infection and investigated whether it contributed to aMPV/C-mediated cellular dysfunction." (PMID 32231136, 2020). "At 28 days post-infection, qPCR results showed that miR-27a antagomir treatment dramatically suppressed miR-27a expression in lung tissues and spleens of the mice, and increased the expression of Plk2 and Pink1, the two characterized miR-27a’s targets, in the lung tissues 40,41." (PMID 30327467, 2018).
cardiovascular disease (2 papers, 2020 to 2021). "There is first evidence that PLK2 regulates fibrosis formation in cardiovascular disease and differential regulation of PLK2 gene expression was found in Transforming Growth Factor beta 1 (TGF-β) treated adult lung fibroblasts." (PMID 33799608, 2021).
bacterial infection (1 paper, 2024). "The down-regulated expression of so-called cell death related genes, including plk2 among others, and the up-regulated expression of inflammation related genes, including il6 among others, was shown in the hybrid grouper Epinephelus fuscoguttatus x Epinephelus lanceolatus after bacterial infection." (PMID 38983863, 2024).
neurological diseases (1 paper, 2022). "PLK2 is known to phosphorylate α-synuclein, one of the non-amyloid components that accumulate in neurological diseases such as Alzheimer’s." (PMID 36232565, 2022).
PLK2 also shares sentences with these, for which no sentence is quoted: gastric cancer (3 papers); multiple myeloma (3); bladder cancer (2); myelodysplastic syndrome (2); Parkinson (2); polycystic ovary syndrome (2); adenoma (1); anemia (1); astrocytoma (1); atrial fibrillation (1); chondroblastic osteosarcoma (1); cognitive decline (1); colorectal (1); endometriosis (1); fibrosis (1); head and neck cancer (1); head and neck squamous cell carcinoma (1); hematopoietic diseases (1); irritable bowel syndrome (1); laryngeal squamous cell carcinoma (1); lung carcinoid tumour (1); movement disorder (1); myeloproliferative neoplasm (1); Myocardial fibrosis (1); oligodendroglioma (1); osteoblastic osteosarcoma (1); osteoporosis (1); parasite infection (1); prediabetes (1); premature ovarian failure (1).
A further 5 diseases each share a sentence with PLK2 in 1 paper.